PRPF4 (pre-mRNA splicing tri-snRNP complex factor PRPF4)
Description:
Plays a role in pre-mRNA splicing as component of the U4/U6-U5 tri-snRNP complex that is involved in spliceosome assembly, and as component of the precatalytic spliceosome (spliceosome B complex).
Synonyms: hPrp4; PRP4; Prp4p; HPRP4P; SNRNP60; RP70
Tractability: Small molecule: a structure with a bound ligand is known; it belongs to a druggable protein family. PROTAC: ubiquitination databases record sites on it; its protein half-life has been measured.
Target class: Other nuclear protein
Gene: Protein-coding gene on chromosome 9 (113,275,642 to 113,294,009, forward strand). Ensembl gene ENSG00000136875.
Subcellular location: Nucleus; Nucleus speckle
Subcellular location (Human Protein Atlas): Nuclear speckles
Pathways (Reactome):
Metabolism of RNA: mRNA Splicing - Major Pathway
Gene Ontology:
Molecular function: protein binding; U4 snRNA binding; U6 snRNA binding
Biological process: mRNA splicing, via spliceosome; RNA processing; RNA splicing; RNA splicing, via transesterification reactions; spliceosomal complex assembly; spliceosomal snRNP assembly; spliceosomal tri-snRNP complex assembly; spliceosome conformational change to release U4 (or U4atac) and U1 (or U11)
Cellular component: Cajal body; nuclear speck; nucleus; precatalytic spliceosome; spliceosomal complex; spliceosomal snRNP complex; U12-type precatalytic spliceosome; U2-type precatalytic spliceosome; U4/U6 snRNP; U4/U6 x U5 tri-snRNP complex; nucleoplasm; U4 snRNP; U4atac snRNP; U4atac/U6atac snRNP; U4atac/U6atac x U5 tri-snRNP complex
Genetic constraint (gnomAD): Loss-of-function variants: 14 observed, 74.53 expected, observed/expected ratio (o/e) 0.19, 90% interval 0.12 to 0.29. The upper end of that interval is the gene's LOEUF score, 0.29, which puts it in group 1 of 6, group 1 being the genes least tolerant of losing a copy. Missense variants: 478 observed, 685.78 expected, observed/expected ratio (o/e) 0.7, 90% interval 0.65 to 0.75. Synonymous variants: 225 observed, 244.11 expected, observed/expected ratio (o/e) 0.92, 90% interval 0.83 to 1.03.
Gene-disease validity (ClinGen):
ClinGen rates the evidence that PRPF4 causes each of these diseases.
inherited retinal dystrophy (autosomal dominant): Moderate. An instance of retinal degeneration that is caused by an inherited modification of the individual's genome.
Homologues: Orthologues: chimpanzee PRPF4 (100% identical), pig PRPF4 (99% identical), rabbit PRPF4 (99% identical), macaque PRPF4 (99% identical), dog PRPF4 (99% identical), mouse Prpf4 (99% identical), guinea pig Prpf4 (99% identical), rat Prpf4 (99% identical), zebrafish prpf4 (78% identical), Drosophila melanogaster U4-U6-60K (52% identical), Caenorhabditis elegans prp-4 (41% identical).
Diseases named in the same sentence as PRPF4 in open-access papers:
PRPF4 is named in the same sentence as 17 diseases in open-access papers, as found by Europe PMC text mining. Sharing a sentence is not in itself a finding about the gene and the disease. The quoted sentences say what the papers report.
breast carcinoma (5 papers, 2020 to 2024). "PRPF4 affects the growth, migration, invasion, and apoptosis of breast cancer cells through p38 MAPK signaling pathway, which is a therapeutic target for breast cancer." (PMID 39095659, 2024). "PRPF4, which is part of the U4/U6 di-snRNP, was found to be overexpressed in breast cancer cell lines." (PMID 34065983, 2021). "Pre-mRNA processing factor 4 (PRPF4) is known as a novel therapeutic target for breast cancer treatment." (PMID 34686726, 2021). "The PRPF4 gene was overexpressed in various breast cancer cell lines." (PMID 34686726, 2021). "Furthermore, Knockdown of the PRPF4 gene reduced migration and breast cancer invasion via suppressing the p38 MAPK phosphorylation pathway." (PMID 34686726, 2021). "Six breast cancer differentially localized proteins were got: CCNT1, NSUN5, PRPF4, RECQL4, UTP6, ZNF500." (PMID 39095659, 2024). "Silencing PRPF4 resulted in apoptosis, suppression of EMT and reduced migration and invasion of breast cancer cells." (PMID 34065983, 2021). "Based on the results of survival analysis (p < 0.05), it was found that the results of UTP6, NSUN5 and RECQL4 proteins were more relevant to the prognosis of breast cancer, while the results of CCNT1 and PRPF4 were not." (PMID 39095659, 2024).
retinitis pigmentosa (4 papers, 2014 to 2024). Retinitis pigmentosa (RP) is an inherited retinal dystrophy leading to progressive loss of the photoreceptors and retinal pigment epithelium and resulting in blindness usually after several decades. "Mutations found within the gene PRPF4 – which encodes hPrp4 a U4/U6 di-snRNP protein – undertake an important role in the development of retinitis pigmentosa (RP)." (PMID 31080456, 2019). "Mutations in six spliceosomal proteins, PRPF3, PRPF4, PRPF6, PRPF8, PRPF31 and SNRNP200, cause retinitis pigmentosa (RP), a disease characterized by progressive photoreceptor degeneration." (PMID 25383878, 2014). "In addition, we report two cases with retinitis pigmentosa caused by RDH12 (c.524C > T) and PRPF4 (c.1273G > A) pathogenic mutations." (PMID 37264419, 2023).
lung carcinoma (2 papers, 2020 to 2025). "In breast, colon, and lung cancers, overexpression of PRPF4 significantly promotes cell proliferation, invasion, and migration." (PMID 41360772, 2025).
autosomal dominant retinitis pigmentosa (1 paper, 2019). Autosomal dominant retinitis pigmentosa (RP) is an autosomally dominant inherited retinal dystrophy leading to progressive loss of the photoreceptors and retinal pigment epithelium and resulting in blindness usually after several decades. "At least six different proteins of the spliceosome, including PRPF3, PRPF4, PRPF6, PRPF8, PRPF31, and SNRNP200, are mutated in autosomal dominant retinitis pigmentosa (adRP)." (PMID 30967900, 2019).
brain ischemia (1 paper, 2008). Diminished or absent blood supply to the brain caused by obstruction (thrombosis or embolism) of an artery resulting in neurologic damage. "The first gene was precursor mRNA-processing factor 4 (PRPF4) which was found upregulated in global brain ischemia." (PMID 18334927, 2008).
vitiligo (1 paper, 2024). Generalized well circumscribed patches of leukoderma that are generally distributed over symmetric body locations and is due to autoimmune destruction of melanocytes. "Regarding ECA25, six significant genomic regions were identified, although genes related to biological processes associated with vitiligo (TXN, LPAR1, SLC46A2, PRPF4, TRIM32, STOM, BRINP1, and DAB2IP) were only found in five of them." (PMID 39199954, 2024).
cancer (5 papers, 2014 to 2025). A tumor composed of atypical neoplastic, often pleomorphic cells that invade other tissues. "PRPF4 has been associated with increased cell growth and reduced apoptosis in cancer cells, however the specific role of PRPF4 in those processes remains unclear." (PMID 37087509, 2023). "Although it remains to be confirmed if these effects were caused by inhibition of the spliceosome or by a possible other function of PRPF4, the observations suggest that PRPF4 could be a useful target to treat cancer." (PMID 34065983, 2021). "For example, the human ortholog of let-400/prpf-4, has been found to induce G1/S arrest and may function as a cancer suppressor." (PMID 24884423, 2014). "Additionally, PRPF4 contributes to the reversal of cancer cell death induced by anti-cancer drugs by regulating actin cytoskeleton remodeling and epithelial-mesenchymal transition (EMT), highlighting its potential as a novel therapeutic target for cancer." (PMID 41360772, 2025).
PRPF4 also shares sentences with these, for which no sentence is quoted: acrofacial dysostosis (1 paper); cerebrocostomandibular syndrome (1); cervical cancer (1); cutaneous squamous cell carcinoma (1); Ewing sarcoma (1); gastric cancer (1); hepatocellular carcinoma (1); Nager syndrome (1); Noonan syndrome (1); retinal degeneration (1).